IDO1 (indoleamine 2,3-dioxygenase 1)
Diseases named in the same sentence as IDO1 in open-access papers (continued):
Sharing a sentence is not in itself a finding about the gene and the disease.
tumor (continued). "IDO1 is one of the key targets of tumor immunotherapy, but the research on its role in OS progression is still in the initial stage." (PMID 37284323, 2023). "IDO-1 overexpression in tumor cells stimulates Tregs, while reducing effector T and NK cell activities." (PMID 37144580, 2023). "IDO1 upregulation has been shown to have a favorable correlation with not only a dismal prognosis but also tumor advancement and metastasis." (PMID 36860731, 2023). "Significantly lower tumor weights were found in all of the treatment groups, with IDO1/TDO2 inhibition plus PD1 blockade yielding the greatest reductions." (PMID 37226257, 2023). "This clearly demonstrates that IDO1 expression and activity in tumor cells contribute to the impairment of iNKT cell functions induced by the tumor." (PMID 37444608, 2023). "Our data indicated that the proportion of IDO1 high expression in tumor tissues of EC patients was significantly higher than that in normal tissues (P < 0.001)." (PMID 37903782, 2023). "Instead, IDO1 acts as a regulatory node between overarching inflammatory cytokines to support the maintenance of neovasculature already established within the tumor by limiting blood vessel regression." (PMID 37182174, 2023). "The finding of the significant overexpression of the immune checkpoint proteins VISTA and IDO1 in the BM-LUAD compared with the BCBM tumor-rich compartments of the brain metastases should shape lineage-specific brain metastasis therapeutic approaches." (PMID 37061716, 2023). "IDO-1 is related to immunosuppression, which can help tumor cells escape detection by the immune system and promote tumor growth and metastasis." (PMID 37513483, 2023). "The study revealed that overexpression of miR‐153 significantly enhanced T‐cell killing capability and downregulated the expression of indoleamine 2,3 dioxygenase 1 (IDO1) in tumour cells." (PMID 37735815, 2023). "In the retrospective part of this study, we investigated the IDO1 expression in immune cells in primary tumours (PTs) and corresponding lymph node metastases (LNMs) in a homogenous cohort of OSCC patients." (PMID 35963900, 2023). "Tumor cells upregulates IDO1 expression and induce immune tolerance in the tumor microenvironment by depleting the essential amino acid Trp of the substrate and generating toxic metabolites such as Kyn." (PMID 37284323, 2023). "Tumoral cells, through the overexpression of the IDO1 enzyme, greatly enhance l-Trp catabolism via the KP for escaping immune surveillance." (PMID 38201667, 2023). "These phenomena reflected that ICOS and IDO1 expression in both plasma and tissue levels was reflective of unique tumor-microenvironmental features." (PMID 36077704, 2022). "VISTA, IDO1, and PD-L1 are key immune checkpoints, with VISTA and IDO1 appearing more abundant in the stromal compartment of primary tumors, whereas PD-L1 indicated higher expression in their respective tumor compartments." (PMID 35651606, 2022). "The suppressive tumour microenvironment recruits cells expressing IDO1, which in turn recruit and tolerise further immune cells." (PMID 35454819, 2022). "In a recent publication, the immune cell infiltrations (CD3+, FOXP3+, CD8+ T cells, CD20+ B cells) and expressions of PD-1, PD-L1 and IDO1 were evaluated in a cohort of 162 OCCC tumours on a tissue microarray by multiplex immunohistochemistry." (PMID 35043008, 2022). "Both Epacadostat and TCDD treatment led to activation of the AhR reporter, upregulation of IDO1 expression, and the nuclear translocation of AhR in both tumor cells and splenic T cells." (PMID 36163134, 2022). "Due to its key role in tumor immunosuppression, IDO-1 is termed as the “metabolic immune checkpoint”." (PMID 36341334, 2022). "Ido-1 expression in cancer has been described in a wide variety of cells both at the level of the tumor microenvironment and the peripheral blood." (PMID 36419183, 2022).
tumor (continued). "Next, we compared the expressions of four important immune checkpoints (PD-L1, CTLA4, IL4I1, and IDO1) between normal and tumor tissues, and between the two clusters." (PMID 35778697, 2022). "Recently, IDO1 inhibitors have been developed and entered the clinical assessment phase and show promise for cancer therapy by strengthening the anti-tumor immune response." (PMID 35778590, 2022). "Since the LSCC proteomics dataset contained tumours as well as adjacent normal tissues, we next examined the relative enrichment of W>F substitutants and stratified the samples by IDO1 expression." (PMID 35264796, 2022). "CLANsiIDO1 accumulated in TDLNs and tumors, downregulated IDO-1 in both tissues, and improved tumor inhibition by OXA in the CT26 colon cancer model." (PMID 36341334, 2022). "Decreased IDO1 expression inhibits the tumor cell proliferation of colon cancer cells and induces mitotic death and cell cycle arrest in the G2/M phase." (PMID 35760783, 2022). "The effect of IDO1 and kynurenine metabolites cannot be understated, especially their role in tumor immunology." (PMID 36386899, 2022). "Within the TME, IDO1 is broadly expressed in multiple human cancers in tumor, vascular, stromal and immune cells." (PMID 35173722, 2022). "IDO1 promotes immune escape through downregulating natural killer cell receptors, and by mechanism, the tumor cells escape immune surveillance." (PMID 35187162, 2022). "As a part of concerted mechanisms that occur in the TME, a multitude of cancer cells constitutively express or upregulate IDO1, TDO2, or both, and coerce stromal and tumor-infiltrating immune cells to express IDO1, supporting evasion of immunosurveillance." (PMID 35173722, 2022). "Recently, IDO-1 expressing Paneth cells in the stem cell niche of intestinal crypts and tumours were described, which promoted immune escape of CRC." (PMID 35160173, 2022). "Over the past two decades, researchers have paid close attention to IDO1 as a drug target involved in the molecular mechanisms of tumor immune escape." (PMID 35409342, 2022). "Pro-tumoral effects of IDO1 expression were abolished in mice treated with IDO1 inhibitor 1-methyl-tryptophan, proving the key role of tryptophan catabolism in tumor immune escape." (PMID 36188218, 2022). "The study not only demonstrates the feasibility of degrading IDO1 but also provides a method to investigate the role of IDO1 protein in tumor immune evasion." (PMID 36142231, 2022). "Kynurenine accumulation is also frequently found in the TME and results from an overexpression of indoleamine 2,3-dioxygenase 1 (IDO1) or tryptophan 2,3-dioxygenase 2 (TDO) in tumor and/or tumor-associated cells (e.g., MDSCs or cancer-associated fibroblasts)." (PMID 36358860, 2022). "Amount of evidence suggest that IDO1- or TDO2-expressing tumor cells can escape immunosurveillance via Trp starvation, and AhR is involved in tumor immune evasion." (PMID 35173722, 2022). "Then, to explore the correlation between the expression level of IDO1 and the development of TNBC, we constructed stable overexpression of IDO1 and stable interference with IDO1 in 4T1 cell lines and constructed xenograft tumor models." (PMID 36550159, 2022). "CD8 + T cells in the tumor microenvironment can produce interferon-γ (IFNγ) to stimulate the up-regulation of PD-1/PD-L1 and IDO1 gene expression." (PMID 36059531, 2022). "We selected levels of secreted kynurenine as our readout as this is directly connected with activity of IDO1, which, in addition to being an immune checkpoint protein, is also a surrogate marker of tumor cell immune activation." (PMID 35150740, 2022). "CSCs can recruit immunosuppressive properties of DCs by producing immunosuppressive cytokines, including IL-13, IL-10, IL-4, and co-inhibitory molecules like B7-H3, IDO1 and PD-L1 which induce tumor properties of DCs." (PMID 36207500, 2022).
tumor (continued). "The enzyme IDO-1 in tumor catalyzed the cleavage of L-tryptophan and production of kynurenine which promoted the function of immunosuppressive Tregs." (PMID 36510194, 2022). "Preclinical studies suggested that the addition of IDO1 blockade into local RT reduced tumor growth, decreased regulatory T cells, and even reversed T-cell exhaustion in the TME with good tolerance." (PMID 36032151, 2022). "This difference was statistically significant between the bladder tumor tissues and the adjacent normal tissues, and IDO1 expression was significantly correlated with tumor size, T stage, and N stage." (PMID 35918736, 2022). "It has been observed in several studies that IDO1 + DCs lead to local T-cells deactivation and suppress the host’s anti-tumor T-cells response." (PMID 35681736, 2022). "As an anti-inflammatory mediator, IDO1 is also essential for the resistance of host-microbiome homeostasis and is produced by tumor cells and following the activation of TLR4 and TLR9 in DCs that induces immune responses against tumors." (PMID 35463305, 2022). "Clinically, IDO1 overexpression has been observed in multiple tumor indications, which correlates with CD8+ T cell infiltration and other immunosuppressive pathways." (PMID 35780226, 2022). "Since the tumors arose from human PDAC cells in a mouse xenograft, we monitored the expression of IDO1 mRNA specifically in tumor cells by using primers specific for human IDO1." (PMID 35997090, 2022). "Collectively, these data demonstrated that USP14 functioned as a key regulator of immune suppression by modulating IDO1 levels in tumor cells." (PMID 36163134, 2022). "IDO1 overexpression within tumor beds leads to tryptophan deprivation, which impairs antitumor immune functions." (PMID 35159363, 2022). "The crucial role of IDO1 is attributed to the kynurenine (Kyn) pathway of tryptophan (Trp) metabolism, both of which play a role in inhibiting the anti-tumor activation of effector T cells." (PMID 36545214, 2022). "A central concept behind IDO1 inhibitor development for cancer centered on the TRP-dependent cross-talk in the TME between IDO1-expressing tumor, myeloid cells, and T cells whose proliferation would be suppressed by local TRP restriction." (PMID 35245456, 2022). "Apoptotic and necrotic tumor cells, via efferocytosis and IDO1, respectively, promote tumor “homeostasis” and progression." (PMID 36059952, 2022). "IDO1 in tumor cells, the dominant cell type in NSCLC, metabolizes Trp and reduces its availability for immune cells, leading to suppression of CD8+ T cells and expansion of Tregs." (PMID 36068203, 2022). "Tumor cells can release various immunosuppressive factors, such as adenylate, indoleamine 2,3-dioxygenase 1 (IDO), prostaglandin E2 (PEG2), interleukin-10 (IL-10), and transforming growth factor-β (TGF-β), to inhibit the activation of immune cells." (PMID 35223466, 2022). "Using athymic nude mice, we demonstrate that carbidopa-mediated suppression of IDO1 expression attenuates tumor growth." (PMID 35997090, 2022). "As expected, PD-L1 and IDO1 expression were elevated in DDIR-positive tumours, given that these genes are constituent parts of the signature; however, upregulation of non-signature checkpoint genes was also seen in the transcriptomic data." (PMID 34728791, 2022). "Studies have shown that IDO1 exerted a powerful immunosuppressive effect through local tumor microenviroment inhibition of T lymphocytes and other immune cells." (PMID 35187162, 2022). "Nowadays, attention has been focused on the effects of IDO1, because in addition to immune regulation, activation of the IDO1/Kyn/AHR axis affects tumor cell viability, proliferation, and apoptosis in vitro." (PMID 35371054, 2022). "IDO1-mediated tryptophan metabolism plays an important role in creating an immunosuppressive tumour microenvironment." (PMID 36163134, 2022). "The relation between CAFs and IDO1 in forming the tumor immune microenvironment remains further studied and explored." (PMID 35681736, 2022).
tumor (continued). "Previous studies have shown that IDO1 and 2 can suppress anti-tumor immune response by activating CD4+CD25+Foxp3+ regulatory T cells (Treg) and myeloid-derived suppressor cells (MDSCs), which consequently inactivate CTLs." (PMID 35656514, 2022). "Tumors from 4T1 cells stably overexpressing IDO1 grew faster and exhibited greater tumor volume compared to vector control groups." (PMID 36550159, 2022). "The findings suggest that reducing the expression level of IDO1 can help inhibit the proliferation of tumor." (PMID 36550159, 2022). "Our results present OATD-02 as an attractive option for combination with other immunotherapeutics, such as PD-1/PD-L1 antibodies or IDO1 inhibitors, especially in the therapy of particularly resistant hypoxic tumours." (PMID 36010962, 2022). "More generally, these data suggest that CARD9-NF-kβ-IDO1 and IL-6-STAT3-NF-kβ-IDO1 are vital tumor immunomodulatory pathways in MDSCs." (PMID 35681736, 2022). "In preclinical cancer models, the IDO1/TDO inhibitor RG70099 demonstrated significant decrease Kyn levels, while reduced tumor volumes was reported in response to the IDO1/TDO inhibitor EPL-1410 when evaluated as single agent." (PMID 35173722, 2022). "Significantly, IDO1 enzyme has a leading effect on the anti-tumor responses of NK cells and its interactions with other TME-related cells." (PMID 35681736, 2022). "The expression level of IDO1 closely correlates with poor prognosis of tumor, and IDO1 inhibitors have shown significantly limit tumor growth." (PMID 35681736, 2022). "The expression levels of other hub genes CTLA4, CXCL10, CCL5, CCl4, ICAM1, CXCL9, CD27, GZMB, FCGR2A, SELL, IDO1 in SKCM were higher than those in non-tumor skin tissues (P < 0.05), and the results were statistically significant." (PMID 35710862, 2022). "The upregulation of IDO1 expression is positively correlated with a poor prognosis and tumor progression and metastasis." (PMID 35800989, 2022). "In light of these considerations, the blockage of the IDO1 pathway in ECs appears as an attractive treatment option, as IDO1 provides a direct mechanism of tumor protection against attack by closely located or contacting T lymphocytes." (PMID 36119020, 2022). "IDO1 metabolism depletes the tumor microenvironment of tryptophan, leading to T cell starvation and impaired activation." (PMID 35150740, 2022). "In this case, miR-153 was found to act as an anti-tumor molecule in colon cancer by suppressing the Indol amine 2,3-dioxygenase 1 (IDO1) enzyme that catalyzes tryptophan kynurenine and 3-hydroxyanthranilic acid immunosuppressive metabolites." (PMID 36419058, 2022). "Because IDO1 is an important immune checkpoint modulator, it is important in tumor immune escape, and thus is an important therapeutic target in cancer therapy." (PMID 36408235, 2022). "In 2003, our group discovered that tryptophan catabolism by tumor lines expressing constitutively IDO1 prevented their immune rejection." (PMID 36188218, 2022). "IDO1 induces tumor-related immunosuppression by Trp depletion and Kyn accumulation, which result in dysfunction of natural killer (NK) cells/effector T cells and activate Tregs." (PMID 36233312, 2022). "Activated T cells infiltrating the tumour microenvironment secrete interferon-γ (IFNγ) that induces expression of the enzyme IDO1 in cancer cells." (PMID 35264796, 2022). "Clinical studies revealed that IDO1 inhibitors combined with chemotherapy or ICIs elicit tumor regression." (PMID 36341388, 2022). "This nanoplatform significantly activated effector T-cells via persistent IDO1 degradation, dually inhibiting tumor growth and metastasis." (PMID 36080223, 2022). "The IHC assay showed that tumor samples of smoker patients had higher levels of IDO1 expression and higher immunoreactivity score (IRS) than those of nonsmoker patients." (PMID 36068203, 2022).
tumor (continued). "IDO1 overexpression is shown to deplete tryptophan in the microenvironment, thereby suppressing T-cell function and leading to the immune escape of tumor cells." (PMID 36714107, 2022). "Intra-tumour T cell activity, high level of IDO1, and certain oncogenic signalling pathways are thus proposed to stimulate W>F substitutants." (PMID 35264796, 2022). "Densitometry analysis of western blot bands confirmed that smoker patients had higher values of IDO1 in tumor tissue (IDO1tumor) to IDO1 in normal tissue (IDO1normal) ratio than nonsmoker patients." (PMID 36068203, 2022). "Because IDO1 expression is found in tumor cells of different types of cancers, many studies report that a high IDO1 expression is associated with a negative effect on prognosis." (PMID 36119020, 2022). "NLG919 downregulated IDO‐1‐mediated immunosuppression and inhibited Tregs, leading to the suppression of tumor metastasis." (PMID 34796689, 2022). "Our results indicate that IDO1 macrophages play an important role in tumor immunity, and patients with CRC having H-IDO1M were more suitable for immunotherapy." (PMID 36248886, 2022). "Tumor draining lymph nodes tend to be the areas of highest IDO1 expression, particularly on the surface of APCs, with research suggesting this expression contributes to a tumor’s ability to form locoregional metastases, as seen in breast models." (PMID 36031601, 2022). "The synergistic effects of PD-L1 and IDO-1 inhibition resulted in a greater activation of tumor-infiltrating CTLs, an increase in tumor cell apoptosis and a higher survival time in treated mice, when compared with free siPD-L1 or the IDO-1 inhibitor." (PMID 35335881, 2022). "Its activity is employed as an important predictor of immunotherapy response, and the inhibitors of IDO1 are widely studied in tumor combination therapy." (PMID 35571116, 2022). "To further corroborate these data from cell lines and primary tumors, we used the web-based tool GEPIA (Gene Expression profiling Interactive Analysis) and checked the expression profile of IDO1 in PDAC tumor vs. normal pancreas." (PMID 35997090, 2022). "accomplished the concurrent inhibition of IDO-1 in both tumors and tumor-draining lymph nodes (TDLNs) by siRNA-loaded cationic lipid-assisted nanoparticles (CLANsiIDO1)." (PMID 36341334, 2022). "It has been reported that abrine inhibited the activity of indoleamine 2,3-dioxygenase 1 (IDO1), the important immunoregulatory enzyme, and suppressed tumor growth." (PMID 35602291, 2022). "IDO1, which is expressed in multiple types of malignancies from the tumor microenvironment (TME), catalyzes the oxidation of tryptophan (TRP) to immunosupressive metabolite N-formylkynurenine." (PMID 36034879, 2022). "Tumor and stromal cells increase the expression of the enzyme IDO1, which metabolizes tryptophan into the immunosuppressive kynurenine." (PMID 36713558, 2022). "Since PDAC cells also overexpress IDO1, and because IDO1 has a context-dependent function, would it rather be more beneficial to inhibit IDO1 in tumor cells?" (PMID 35997090, 2022). "IDO1 expression was increased in tumor tissues in KIRP and HNSC, predicting worse OS in KIRP but better OS in HNSC." (PMID 36059952, 2022). "Previous findings support the role of IDO1 with regard to the polarization of macrophages to restrain excessive or inappropriate immune activation in inflammatory or tumor microenvironments." (PMID 36553530, 2022). "We first sought to characterize the expression of IDO1/TDO2 in human tumors as a validation for elimination of their product Kyn to boost anti-tumor immunity." (PMID 35780226, 2022). "IDO1 expression is correlated with increasing tumor grade, as well as the expression of other immunosuppressive mediators such as PD-L1." (PMID 36011015, 2022). "In vivo data demonstrated that silencing IDO1 suppressed tumor growth and potentiated the anticancer action of DDP." (PMID 36233312, 2022).